MTOR (mechanistic target of rapamycin kinase)
Diseases named in the same sentence as MTOR in open-access papers (continued):
Sharing a sentence is not in itself a finding about the gene and the disease.
breast cancer (continued). "The outcome measures were hazard ratios (HRs) with 95% confidence interval (CI) for the association between the prognosis of breast carcinoma patients and p-mTOR expression." (PMID 28114374, 2017). "The present study evaluated the correlation between mTOR rs2536/rs2295080 polymorphisms and breast cancer risk." (PMID 27533457, 2016). "Taken together, our data highlight the activation of IGF1R/p110β/AKT/mTOR as a mechanism of resistance to BYL719 in PIK3CA-mutated breast cancer cells." (PMID 27048245, 2016). "In summary, inhibition of components of the PI3K/Akt/GSK3/mTOR in EGFR-overexpressing MDA-MB 468 breast cancer and HCT8 colon cancer cell lines is associated with inhibitor-specific changes in PCho content." (PMID 27811956, 2016). "PI3K/mTOR pathway aberrations are common in breast cancer and associated with resistance to endocrine and human epidermal growth factor receptor 2 (HER2) targeted therapies." (PMID 27155197, 2016). "The decreased mTOR protein degradation is one of the potential causes underlying the high mTOR protein level in breast cancer cells." (PMID 27748082, 2016). "Collectively, these results demonstrated that the HER2+/PIK3CAmut breast cancer cells are highly susceptible to mTOR-targeted growth suppression, which is mediated through cell cycle blockade and induction of apoptotic cell death." (PMID 27563814, 2016). "The association between mTOR rs2536 polymorphism and breast cancer risk was undetectable in our study (P > 0.05)." (PMID 27533457, 2016). "The mTOR pathway is implicated not only in tumorigenesis of breast cancer but also in tumor sensitivity to chemotherapy and hormonal treatment." (PMID 27748082, 2016). "To understand possible mechanisms underlying elevated level of mTOR protein accumulation in breast cancer, we have undertaken this work." (PMID 27748082, 2016). "In light of the ability of mTOR activation to influence a wide-range of cell functions, it is likely that genetic variations of mTOR affects the risk level of breast cancer, and even the clinical outcome for breast cancer patients." (PMID 27533457, 2016). "In recent years oral mucosal injury has been increasingly recognized as an important toxicity associated with mammalian target of rapamycin (mTOR) inhibitors, including in patients with breast cancer who are receiving everolimus." (PMID 27334013, 2016). "This case-control study examined the association between mTOR rs2536/rs2295080 polymorphisms and breast cancer risk." (PMID 27533457, 2016). "Hyperactivation of mTOR signaling has been associated with aggressive tumor growth in many cancers 8, including breast cancer." (PMID 27748082, 2016). "Consistent with these meta-analyses, we found the association between mTOR rs2295080 polymorphism and decreased breast cancer risk." (PMID 27533457, 2016). "In conclusion, our present study provides evidence of the association between mTOR polymorphisms and breast cancer risk." (PMID 27533457, 2016). "Mutations in the PI3K/AKT/mTOR pathway are frequent in breast cancer, and activation of this pathway via molecular aberrations in PIK3CA, PIK3CB, PIK3R1, AKT, TSC1/2, and PTEN promotes resistance to HER2-targeted therapies." (PMID 27923043, 2016). "In parallel, the significant effects were observed between mTOR rs2295080 polymorphism and breast cancer risk in the allele, codominant, and recessive models (P < 0.05)." (PMID 27533457, 2016). "The phosphoinositide 3 kinase (PI3K)/Akt/mammalian target of rapamycin (mTOR) (PAM) pathway is frequently activated in breast cancer, with PIK3CA being the most commonly mutated gene of significance in estrogen receptor (ER) positive breast cancer." (PMID 26779371, 2015). "Several studies have shown that targeting Akt or mTOR restores the response to tamoxifen or trastuzumab in breast cancer cells, which implies causative effects of hyperactivation of Akt/mTOR during the development of drug resistance." (PMID 26158266, 2015).
breast cancer (continued). "Cellular GAS5 expression suggest a role of GAS5 in the regulation of apoptosis in breast cancer cell lines and tumors and an inverse association with the mTOR expression in PCa cell lines." (PMID 25999983, 2015). "Next to a small set of classical disease-defining genes such as BRCA-1/2, the estrogen receptor or HER2/neu, the canonical PI3K/AKT/mTOR signaling pathway forms another mutational hotspot in breast cancer." (PMID 26498353, 2015). "Increased PI3K/mTOR signaling occurs in up to a quarter of breast cancers and upregulation of Akt signaling is associated with resistance to both endocrine and HER2 targeted therapies." (PMID 25889650, 2015). "In the COSMIC database, mTOR mutation was found in 20 breast cancers; moreover, the frequency of mTOR mutation was only 2.45% in all types of tumors that have been reported." (PMID 25816324, 2015). "Activating mutations in PIK3CA deregulate the PI3K/AKT/mTOR pathway and are frequent in breast cancer." (PMID 26148118, 2015). "Our previous studies demonstrate that CXCL6/CXCR6 chemokine axis induces prostate cancer progression by the AKT/mTOR signaling pathway; however, its role and mechanisms underlying invasiveness and metastasis of breast cancer are yet to be elucidated." (PMID 25909173, 2015). "Dysregulation of mTOR signaling occurs in various tumor types, including breast cancer, and has been associated with cancer pathogenesis, disease progression, and treatment resistance." (PMID 26421002, 2015). "Further, rapamycin inhibition of mTOR lowered NS levels in PTEN-mutated MDA-MB-468 breast carcinoma cells." (PMID 25880415, 2015). "These properties are consistent with those reported for a number of other hormone-resistant breast cancer lines, where resistance to inhibitors of the mTOR/Akt pathway is generally associated with increased resistance to a broad variety of cytotoxic agents." (PMID 25232533, 2014). "Together these data suggested the possibility that an activated mTOR pathway, possibly associated with mTORC1, is a good prognostic factor in primary human ERα + breast cancer." (PMID 24887419, 2014). "Through miR-155 overexpression in the ER+ MCF-7 breast cancer cell line we demonstrate alterations in the mTOR signaling cascade can result in the loss of PgR expression without prior growth factor stimulation." (PMID 25283550, 2014). "The present study implicated the PI3K/AKT/mTOR pathway in the regulation of FASN expression in ER/HER2-positive breast cancer cells and demonstrated that rapamycin, an mTOR inhibitor, inhibited FASN expression." (PMID 24866893, 2014). "Increased utilization of the PI3K/mTOR pathway in ER+ breast cancer has been associated not only with endocrine resistance but also with resistance to a variety of cytotoxic drugs." (PMID 25232533, 2014). "In preclinical models, mTOR inhibitors synergize with trastuzumab and have shown to cause complete regression of mouse Her-2-positive mammary tumors." (PMID 24684785, 2014). "Previous studies have shown loss of PgR expression in clinical samples is used as an indicator of aberrant growth factor signaling and the IGF induced AKT/mTOR signaling pathway is commonly associated with the repression of PgR in breast cancer systems." (PMID 25283550, 2014). "In breast cancer cells, mTOR signaling is linked through phosphatidylinositol 3-kinase (PI3K) and Akt/protein kinase B (PKB) to signaling from external cellular receptors such as EGFR." (PMID 25232533, 2014). "HER2-mediated activation of the PI3K/Akt/mTOR pathway has been implicated in the angiogenesis and metastasis of breast cancers, and is predictive of tumor progression." (PMID 25364442, 2014). "Hyperactivation of the mammalian target of rapamycin (mTOR) pathway is associated with breast cancer progression and with the development of endocrine resistance." (PMID 23404211, 2014).
breast cancer (continued). "Aberrations in phosphatidylinositol 3-kinase (PI3K)/mTOR pathway protein expression are also associated with poor prognosis in HR+ breast cancer." (PMID 23404211, 2014). "As such, inhibition of this pathway is a clinical priority, particularly as overactivation of the PI3K/Akt/mTOR pathway has been associated with drug resistance in breast cancer." (PMID 25153725, 2014). "Preclinical studies have shown that breast cancer cell lines with alterations in the PI3K/Akt/mTOR pathway, such as activating PIK3CA mutations or HER2 amplification, are sensitive to PI3K/Akt/mTOR pathway inhibition." (PMID 25209360, 2014). "In patients with invasive breast cancer, increased activation of this pathway is associated with poor prognosis and, thus, mTOR has recently been recognised as an important drug target for breast cancer therapy." (PMID 24457069, 2014). "Results from the present study show that the CoCl2-induced hypoxic response in +SA mammary tumor cells caused a large increase in Akt/mTOR signaling proteins associated with promoting HIF-1α expression, and compound 44 blocked this response." (PMID 25140303, 2014). "In this study, we demonstrate that there is also a FMC subset defined as TN FMC, which is characterised by a statistically significant association with m-TOR and p-mTOR expression as demonstrated in human breast cancer." (PMID 23587222, 2013). "This study is the first to characterise biomarkers and mutations in the PIK3CA/mTOR pathway in familial male breast cancer noting several novel observations." (PMID 23971979, 2013). "Mutational activation of the PI3-kinase-Akt-mTOR pathway is the most frequent oncogenic event in breast cancer, with a particular predilection for the hormone receptor-positive subtype of disease." (PMID 23237847, 2013). "The enhanced glycolytic metabolism observed in LKB1-deficient breast cancer cells was reversed by mTORC1 inhibition, suggesting that elevated mTOR signaling downstream of LKB1 drives the metabolic phenotype of these cancers." (PMID 24280377, 2013). "The phosphatidylinositol 3-kinase (PI3-kinase)-Akt-mTOR pathway is mutated at high frequency in human breast cancer, and this pathway is the focus of active drug discovery and clinical investigation." (PMID 23237847, 2013). "Trials combining hormonal therapies with mTOR inhibitors are been performed in breast cancer, since resistance to hormonal therapy has been associated with overactivation of the mTOR pathway." (PMID 22408430, 2012). "In breast cancer, which is characterized by rapid growth, invasion, and metastasis, PR was associated with pathways involving mTOR and Wnt signaling and apoptosis." (PMID 22272226, 2012). "Remarkable activity was seen in breast cancer patients in a phase I dose finding study of oral mTOR inhibitor ridaforolimus associated to IGF-1R monoclonal antibody, MK-0646 (dalotuzumab)." (PMID 22415797, 2012). "More recently, it has been shown that HER2 overexpression in breast cancer is often associated with aberrant activation of the mTOR pathway." (PMID 21961653, 2011). "Since the PI3K/PTEN/Akt/mTOR pathway is frequently altered in breast cancer and associated with drug resistance, we used a retrovirus to stably-transfect MCF-7 cells with a constitutively-active Akt-1 gene [ ΔAkt-1(CA)]." (PMID 21881167, 2011). "The Fbxw7/hCdc4 isoform responsible for mTor degradation was not defined in this study, but it's noteworthy that mTor localizes to the cytosol and that breast cancer cells with loss of Fbxw7/hCdc4 were shown to be more sensitive to mTor inhibitors." (PMID 21122106, 2010). "We demonstrate that inhibitors of growth factors such as gefitinib and lapatinib can induce autophagy in breast cancer cells, and the nutrient depletion-induced autophagy is associated with activation of eEF-2 kinase via the mTOR/S6 kinase signaling pathways." (PMID 20300520, 2010).
breast cancer (continued). "For example, the HER2 overexpression observed in about one-third of breast cancers is associated with activation of PI3-kinase/Akt/mTOR signalling, resistance to stress-induced apoptosis, and tumour aggressiveness." (PMID 19127256, 2009). "A recent study showed that mutation perturbing the lipid and protein phosphatase activities of PTEN caused activation of Akt/mTOR/p70S6K signaling and chemoresistance, whereas rapamycin synergized with doxorubicin to inhibit growth of breast cancer cells." (PMID 19430575, 2008). "Furthermore, ERα is associated with mTOR signaling in breast cancer cells, making it a potential therapeutic target." (PMID 40937413, 2025). "CCL2 is a key chemokine involved in cancer development, with signaling pathway significantly contributing to the progression of various cancers The CCL2 drives tumor growth through the PI3K/AKT/mTOR pathway, which is associated with poor prognosis in breast cancer." (PMID 40761779, 2025). "The phosphoinositide 3‐kinase (PI3K)/protein kinase B (PKB or AKT)/mammalian target of rapamycin (mTOR) signaling pathway (PAM pathway) plays a critical role in breast cancer pathogenesis and progression, and is closely linked with resistance to endocrine therapy in advanced breast cancer." (PMID 40206206, 2025). "Proteomic analysis of breast cancer cell lines harboring Y537N and Y537S ER mutations has revealed a significant upregulation of immune-related pathways, along with increased proliferation signaling and activation of key kinases, particularly mTOR and CDKs." (PMID 40244377, 2025). "Mutations in the PI3K/mTOR/Akt pathway are found in up to 70% of all breast cancers." (PMID 40019775, 2025). "Consequently, with its targeting of both the FRB and the kinase domains of mTOR, RapaLink-1 has demonstrated the ability to target breast cancer cells with somatic mutations in mTOR, FRB, or the kinase domain, which typically confer drug resistance." (PMID 38474373, 2024). "Furthermore, DEPDC1 has been implicated in promoting aggressive features in breast cancer by activating the PI3K/AKT/mTOR pathway." (PMID 39068164, 2024). "The signaling pathway involved in cell proliferation and survival, phosphoinositide 3-kinase (PI3K)/protein kinase B (Akt)/mammalian target of rapamycin (mTOR) or (PI3K/AKT/mTOR), is often dysregulated in breast cancer and is associated with endocrine therapy resistance." (PMID 38538285, 2024). "Moreover, CCL2 secreted by TAMs has been linked to the induction of tamoxifen resistance in breast cancer cells through the PI3K/Akt/mammalian target of rapamycin (mTOR) pathway." (PMID 39286635, 2024). "MAPK3’s involvement in cell proliferation and survival, alongside PIK3CA and mTOR’s roles in metabolic regulation and tumor progression, underlines their contribution to breast cancer pathophysiology, particularly in aggressive subtypes like TNBC and HER2-positive cancers." (PMID 39850811, 2024). "PI3K/AKT/mTOR pathway is implicated in breast cancer progression and recurrence." (PMID 39448637, 2024). "In 2019, the FDA approved the use of alpelisib in combination with fulvestrant for hormone receptor-positive and HER2-negative advanced breast cancer patients harboring PIK3CA-mutation suggesting the importance of inhibition of PI3K/AKT/mTOR axis in hormone receptor-positive breast cancers." (PMID 37900137, 2023). "The Akt/mTOR-dependent pathway is a predominant signalling pathway associated with breast cancer, and many clinical trials have confirmed that targeting this pathway could lead to promising therapeutic activity." (PMID 37176840, 2023). "Here, we hypothesize that the CXCL12/CXCR4/mTOR/HIF-1α axis in DPP-4-deficient cells plays a key role in the activation of autophagy in breast cancer cells to promote survival." (PMID 37760498, 2023).
breast cancer (continued). "The phosphoinositide 3‐kinase (PI3K)/protein kinase B (AKT)/mammalian target of rapamycin (mTOR) (PI3K/AKT/mTOR) signaling pathway is the most commonly mutated pathway in HR‐positive breast cancer, and abnormal activation of this pathway is highly correlated with resistance to endocrine therapy." (PMID 38090370, 2023). "In addition, the positive correlation between the expression of the transient receptor potential channel 5 (TRPC5) and autophagic states is associated with the CaMKKβ/AMPKα/mTOR/p70S6K signaling pathways in adriamycin-resistant breast cancer cells." (PMID 36677797, 2023). "Few studies have looked at the relationship between cellular factors that are common in breast cancers and the mTOR pathway’s genetic variation and breast cancer risk, and subtypes and only a small number of single-nucleotide polymorphisms (SNPs) have been examined." (PMID 36831624, 2023). "Furthermore, the mTOR/HIF-1α axis is associated with breast cancer biology, including epithelial mesenchymal transition (EMT), invasion, metastasis, and resistance to chemotherapy." (PMID 37760498, 2023). "In addition to genetic activation, mTOR can be activated by PI3K signaling, which has been associated with drug resistance, and mTOR inhibition re-sensitizes ER+ breast cancer cells to tamoxifen." (PMID 36979714, 2023). "Physical activity (PA) is associated with decreased signaling in the mTOR pathway in animal models of mammary cancer, which may indicate favorable outcomes." (PMID 36895729, 2023). "Aberrant activation of the mammalian Target of Rapamycin (mTOR) pathway has been linked to obesity and endocrine therapy resistance, factors that may contribute to Black-White disparities in breast cancer outcomes." (PMID 35608730, 2022). "PI3K/AKT/mTOR inhibition caused by MED16 knockdown may lead to a slower proliferation of breast cancer cells and autophagy enhancement, which leads to a decreased sensitivity to tamoxifen." (PMID 36294896, 2022). "Thus, our study supports a model for active AMPK signalling with concomitant loss of mTOR signalling in breast cancer stemness." (PMID 35195687, 2022). "We, therefore, hypothesized that GATA3 loss may induce addiction to mTOR signaling in breast cancer cells." (PMID 35440675, 2022). "However, in another case, the mTOR signaling pathway played a role in accelerating DNA damage caused by deletion of the breast cancer-related gene BRCA1." (PMID 36147481, 2022). "The association of miR-18a and the AKT/mTOR signaling pathway in rendering increased proliferation and migratory abilities to breast cancer cells was recently described and hence lends support to our hypothesis." (PMID 35626709, 2022). "In BRCA1-deficient cells, mTORC2 is overactivated, so BRCA1-deficient breast cancer cells may be dependent on mTORC2 signaling and more sensitive to its inhibition, further suggesting that mTOR plays a role in driving DNA damage events in tumor cells." (PMID 36147481, 2022). "Phosphoinositide 3‐kinase (PI3K)/protein kinase B (PKB or AKT)/mammalian target of rapamycin (mTOR) signaling pathway (PAM pathway) plays an important role in the development of breast cancer and are closely associated with the resistance to endocrine therapy in advanced breast cancer." (PMID 38089455, 2022). "Whether mTOR plays a role in the obesity and breast cancer association warrants confirmation by prospective studies." (PMID 34330319, 2021). "Enhanced activity of mTOR is associated with HER2-overexpressing breast cancers." (PMID 34208071, 2021). "Our findings suggest that mTOR pathway activation indicated by p-mTOR expression may be relevant to the association between body fatness and breast cancer risk." (PMID 34330319, 2021).